CRP (C-reactive protein)
Diseases named in the same sentence as CRP in open-access papers (continued):
Sharing a sentence is not in itself a finding about the gene and the disease.
Respiratory tract infection (continued). "In contrast to many other studies, our study is not limited to the effects of CRP-POCTs on antibiotic prescribing for patients with respiratory tract infections (RTIs)." (PMID 39159989, 2025). "Point of care (POC) CRP can be used to aid the diagnosis and inform antibiotic treatment of respiratory tract infections (LRTIs)." (PMID 39485740, 2024). "This contrasts with the argument that CRP tests can help reduce antibiotic prescribing for respiratory tract infections." (PMID 38184547, 2024). "For instance, a study in Kyrgyzstan evaluated the effectiveness of a CRP point of care test to reduce unnecessary antibiotic prescriptions for children with respiratory tract infections." (PMID 38939359, 2024). "The role of CRP in reducing antibiotic prescription in the primary care of children presenting symptoms of respiratory tract infections has been under evaluation for some time, but results have not always been conclusive enough to make clear recommendations." (PMID 37900677, 2023). "The CRP level was also found to be a valuable preclinical predictor for the subsequent development of an overt respiratory tract infection in this study." (PMID 35201675, 2022). "In some settings, where CRP testing is routinely performed in patients with respiratory tract infections, its use has led to a significant reduction of antibiotic prescriptions." (PMID 36536340, 2022). "Respiratory tract infections were also involved in the release of dd-cfDNA (9.14 ± 15.59%, p = 0.0004), with a positive correlation with C-reactive protein levels." (PMID 35755857, 2022). "The results revealed that elevated nCD64 indexes were significantly associated with respiratory tract infection and bloodstream infections after adjusting for age, gender, temperature, WBC, NLR, CRP, and the counts of T lymphocyte subsets." (PMID 36443747, 2022). "Then we compared the differences in the nCD64 indexes, conventional indicators (WBC, NLR, PCT, CRP), and T lymphocyte subsets among Respiratory Tract Infection Group, Simple Bloodstream Infection Subgroup, and Mixed Bloodstream Infection Subgroup." (PMID 36443747, 2022). "The combined detection of serum SAA, CRP and PCT indicators have higher diagnostic efficiency and can effectively make the differential diagnosis of respiratory tract infection in children." (PMID 35775463, 2022). "A recent meta-analysis supports the conclusion that the benefits of using POC CRP testing in suspected respiratory tract infections outweigh the potential harms, although reduced antibiotic prescribing balanced against an increase in re-consultation rate." (PMID 35892398, 2022). "For respiratory tract infections, C-reactive protein (CRP) point-of-care tests have been used in several countries in the European Union and their effectiveness has been assessed." (PMID 34370115, 2021). "CRP testing in a southeast Asian primary care setting has previously been shown to reduce antibiotic prescribing in patients with respiratory tract infection and our trial extends this evidence base to those with a fever." (PMID 30554748, 2019). "Reduction in antibiotic use in patients with respiratory tract infection was demonstrated after the integration of point-of-care CRP results in clinical algorithms designed for primary care in Tanzania19 and in Vietnam16." (PMID 31664120, 2019). "At onset of CRP increase, six of these 10 patients suffered from respiratory tract infection that resolved during follow up." (PMID 30581413, 2018). "We investigated the diagnostic performance of human neutrophil lipocalin (HNL) in respiratory tract infections compared to those of C-reactive protein (CRP) and procalcitonin (PCT)." (PMID 28468981, 2017). "If POC CRP was available, it was used in 45.5% of the patients who were referred for a suspected respiratory tract infection and in 36.8% of the patients who were referred due to other infections." (PMID 30564668, 2017).
Respiratory tract infection (continued). "In patients treated with antibiotics, the POC CRP was used in 63.3% of respiratory tract infections and 12.8% in other infections when available." (PMID 30564668, 2017). "For instance, CRP levels are typically high in respiratory tract infections, even in patients exhibiting moderately severe CAP." (PMID 26840299, 2016). "The usefulness of CRP testing in acute cough and respiratory tract infection for reducing antibiotic prescription has been assessed repeatedly." (PMID 25655784, 2015). "Point-of-care CRP testing has been shown to be of use in the clinical evaluation of respiratory tract infections in adults and of fever in children." (PMID 25375117, 2014). "Point of care testing for C-reactive protein (CRP) has shown promise as a measure to reduce unnecessary antibiotic prescribing in respiratory tract infections (RTI), but its use in primary care is still controversial." (PMID 24886066, 2014). "The pivotal role of these diagnostic tools is further reinforced by a systematic review and meta-analysis, which found that point-of-care C-Reactive Protein (CRP) testing in primary care is an effective strategy for reducing unnecessary antibiotic prescribing for respiratory tract infections." (PMID 41148668, 2025). "Specifically for CRP, an inaccurate result may lead to inappropriately prescribing or withholding antibiotics in cases of sepsis and respiratory tract infections." (PMID 39485740, 2024). "Erythrocyte sedimentation rate and C-reactive protein levels (except for the child with an on-going respiratory tract infection), differential blood cell counts, total IgA, IgE, IgM, IgG, D-dimer levels, and complement C3 and C4 levels were all unremarkable (not shown)." (PMID 37131308, 2023). "POC CRP testing is cost effective in the primary care management of respiratory tract infections." (PMID 35892398, 2022). "In this case, the POC CRP tests were intended for use in respiratory tract infections where there was uncertainty about whether the infections were bacterial or viral." (PMID 35892398, 2022). "This is in line with earlier studies where it has been shown that CRP testing in respiratory tract infections (RTIs) reduces the antibiotic prescription rate and that it plays a vital role in the decision on whether to prescribe antibiotics or not." (PMID 33399009, 2020). "After adjustment for GRACE risk score and main MI prognosis factors (i.e., CRP, NT-ProBNP levels, LVEF), respiratory tract infection was associated with a threefold increased risk of hospital mortality when compared with other site infections (OR (95%CI) = 2.89 (1.19–6.99), p = 0.02)." (PMID 31212586, 2019). "CRP testing had been reported by a number of researchers to be significantly helpful in reducing the prescription of antimicrobial drugs especially among patients with respiratory tract infections." (PMID 28451028, 2017). "In the present study population, children under 2 years of age showed higher median values of CRP with frequent exposure to comorbidities (mainly diarrhea and respiratory tract infections), conditions that may distort estimates of iron status." (PMID 22574149, 2012). "We showed that the use of CRP in the management of respiratory tract infections in our practice did not cause a reduction in patient satisfaction." (PMID 21880122, 2011). "Therefore, we felt there was a need for a pilot study in an Irish setting to determine the feasibility of near patient CRP testing in routine clinical practice on the treatment of respiratory tract infections." (PMID 21880122, 2011). "C-reactive protein (CRP), a low-cost POCT is commonly used in Scandinavian primary care in managing respiratory tract infections." (PMID 34850657, 2021). "In high income countries, biomarkers such as C-reactive protein (CRP) and procalcitonin, have been shown to be safe, cost-effective, and improve correct antibiotic use in the management of respiratory tract infections in primary care settings." (PMID 29852003, 2018).
Respiratory tract infection (continued). "The diagnostic performance of B-HNL is superior to that of plasma CRP (P-CRP) and plasma PCT (P-PCT) in respiratory tract infections, and the activity specifically reflects bacterial challenge in the body." (PMID 28468981, 2017). "When tests were completed, predominantly in the context of suspected respiratory tract infection, the majority produced low CRP results, which indicated that there would be no benefit from prescribing antibiotics." (PMID 35892398, 2022). "Until further research provides more evidence, POC CRP measurement in children with non-serious respiratory tract infection is not recommended." (PMID 30564733, 2018). "Repeatedly sterile blood cultures, persistently normal CRP, absence of any respiratory symptoms or signs, and normal chest X-rays made the diagnosis of a respiratory tract infection unlikely." (PMID 28683778, 2017). "It is still uncertain whether POC CRP measurement in children with non-serious respiratory tract infection presenting to general practice can reduce the prescription of antibiotics." (PMID 30564733, 2018). "In conclusion, it is still uncertain whether POC CRP measurement in children with non-serious respiratory tract infection presenting to general practice can reduce the prescription of antibiotics." (PMID 30564733, 2018).
peritonitis (71 papers, 2006 to 2026). Inflammation of the peritoneum (tissue that lines the abdominal wall and covers most of the organs in the abdomen). "In patients with peritonitis, especially those in high-risk situations like gastrointestinal perforation, CRP levels greater than 150 mg/L have been linked to increased mortality." (PMID 41170570, 2025). "The considerably increased CRP reflected the severity of the abdominal infection in our patient with concealed peritonitis after stomach perforation caused by the ingested foreign body." (PMID 41441528, 2025). "Those presenting with CRP levels exceeding 3 mg/dl are at an elevated risk for peritonitis and should receive heightened monitoring and prompt, aggressive treatment." (PMID 39726534, 2024). "Of the 240 infection episodes caused by peritonitis, PD-catheter was removed in 12%, and this proportion increased with increasing CRP level (P = 0.040)." (PMID 37314998, 2023). "The results showed that age, decreased serum albumin level, and increased serum CRP levels remained independent risk factors for peritonitis (p < 0.05) in the multivariate analysis." (PMID 32781861, 2020). "We also found that patients in NDN group had a marginally shorter peritonitis-free period than those in DN group and CRP was an independent risk for peritonitis-free survival after adjustment." (PMID 25961883, 2015). "Surprisingly, patients with sustained high levels of hs-CRP had a similar risk of peritonitis compared to that in patients with constant normal hs-CRP values." (PMID 24007461, 2013). "In conclusion, our data demonstrated an association between a progressive increase in hs-CRP levels and peritonitis risk in CAPD patients." (PMID 24007461, 2013). "Mortality (20.5%) was strongly associated with peritonitis, CRP, and NLR (AUC 0.891)." (PMID 41753314, 2026). "A smaller Chinese study (n=258) found that BMI, albumin, albumin/globulin ratio, CRP, and fast peritoneal solute transfer rate were independent risk factors for peritonitis in patients undergoing continuous ambulatory peritoneal dialysis using multivariate logistic regression." (PMID 41001563, 2025). "Notably, our results indicate that CRP level associates with infection severity with regard to longer hospitalization and need for intensive care, and in case of peritonitis, with removal of PD catheter." (PMID 37314998, 2023). "It has been reported that a progressive serum hs-CRP within the first year predicted the first two-year peritonitis risk in PD patients, indicating serum CRP may act as a predictor for short-term peritonitis." (PMID 25961883, 2015). "However, the relationship between a single CRP measurement or variability in CRP levels and the risk of peritonitis in peritoneal dialysis (PD) patients remains uncertain." (PMID 24007461, 2013). "The aim of this study was to evaluate whether a high baseline level of high-sensitivity C-reactive protein (hs-CRP) or changes in the level predicts the risk of peritonitis in patients on continuous ambulatory peritoneal dialysis (CAPD)." (PMID 24007461, 2013). "This may explain the association between the progressive elevation of hs-CRP levels and the development of peritonitis in CAPD patients." (PMID 24007461, 2013). "Similarly, the onset of peritonitis is associated with an increase in serum CRP levels and higher CRP levels have been associated with worse short-term outcomes (e.g., transfer to haemodialysis) and long-term patient outcomes (e.g., subsequent peritonitis event, all-cause mortality)." (PMID 24895536, 2014). "For the complications model, CRP had the strongest impact, followed by appendix diameter and peritonitis." (PMID 41564021, 2026). "Under these circumstances, peritonitis had the strongest influence, followed by CRP, WBC count, and neutrophil percentage." (PMID 41564021, 2026). "In the original analysis, the most important predictors were appendix diameter, peritonitis and CRP respectively for diagnosis, treatment and complications." (PMID 40948509, 2025).
peritonitis (continued). "For severity, our redundancy-aware FS method identified five features: peritonitis, coughing pain, body temperature, thrombocyte count, and C-reactive protein." (PMID 40863881, 2025). "The five features included were peritonitis, coughing pain, body temperature, thrombocyte count, and C-reactive protein." (PMID 40863881, 2025). "Laboratory studies, such as elevated WBC count and CRP levels, can provide some indication of peritonitis, although the sensitivity and specificity of these tests are relatively low." (PMID 40134907, 2025). "The leading features relied upon were peritonitis, white blood cell count, body temperature, weight, severity, and C-reactive protein." (PMID 40863881, 2025). "Frigerio and Bassi reported that PCT levels of 10.0 ng/mL or higher on two consecutive days were superior to C-reactive protein (CRP) levels in predicting septic multiorgan dysfunction syndrome (MODS) in secondary peritonitis patients." (PMID 40566533, 2025). "For management, our redundancy-aware FS method identified 11 features, with the leading features relied upon being peritonitis, white blood cell count, body temperature, weight, severity, and C-reactive protein." (PMID 40863881, 2025). "High CRP levels can be used to independently predict the severity of intractable peritonitis, which is consistent with previous findings." (PMID 38658811, 2024). "The levels of CRP and the rate of erythrocyte sedimentation were found to be higher in patients with secondary peritonitis compared to those with other types of peritonitis." (PMID 38567242, 2024). "Infection and peritonitis with purulent excaudate in the abdominal cavity explained the high CRP and PCT." (PMID 39227528, 2024). "This is partly due to the inflammatory response in the indication for surgery (i.e. near blowout, perforation or peritonitis), and partly contributed to the fact that open surgery generates higher CRP levels than minimally invasive procedures." (PMID 38409295, 2024). "We evaluated eryptosis percentage, CRP, IL-6, and IL-1β levels in the PD controls and in the PD patients with peritonitis on the first day of peritonitis." (PMID 36498493, 2022). "A study of 748 dialysis patients implicated that PTH < 150 pg/mL was associated with elevated inflammatory markers, including tumor necrosis factor α and C-reactive protein, which were traditional evaluated parameters for peritonitis." (PMID 33514340, 2021). "Distributions of several predictors differed significantly (at level α = 0.05) for all three responses, namely, AS, PAS, appendix diameter, body temperature, WBC count, neutrophil percentage, CRP, and peritonitis/abdominal guarding." (PMID 33996697, 2021). "Several SNPs of Fpr1 has been reported previously to be associated with blood pressure 17, C-reactive protein (CRP) level 18, E-selectin expression 19, and inflammatory disease such as aggressive peritonitis 20,21." (PMID 32284754, 2020). "Multivariable proportional hazard analysis identified peritonitis (HR 14.47, CI 2.79–75.00, P = 0.001), average hemoglobin concentration and average serum CRP level as independent predictors of technique failure." (PMID 28158991, 2017). "In this study, we retrieved the DNI, WBC count, neutrophil percentage, and CRP data from the medical records of patients who underwent surgery for peritonitis." (PMID 28763506, 2017). "Among 983 patients with at least 2 hs-CRP data, 334 (34.0%) patients presented total 589 episodes of peritonitis during a cumulative follow-up period of 3601.3 patient-years." (PMID 28676043, 2017). "Peritonitis (HR, 14.47; CI, 2.79–75.00; P = 0.001), average hemoglobin concentrations (HR, 0.75; CI, 0.59–0.95; P = 0.016), and average serum C-reactive protein levels were independent predictors of catheter failure." (PMID 28158991, 2017).